PTH (parathyroid hormone)
Diseases named in the same sentence as PTH in open-access papers (continued):
Sharing a sentence is not in itself a finding about the gene and the disease.
diabetes (continued). "However, it remains unclear whether serum 25OHD, Ca and PTH levels were causally associated with CAD risk in patients with diabetes." (PMID 34602077, 2021). "Therefore, genetic variants that influence serum 25OHD, Ca and PTH levels could serve as instrumental variables (IVs) to determine the impact of serum 25OHD, Ca and PTH levels on the risk of CAD in patients with diabetes." (PMID 34602077, 2021). "Therefore, intermittent PTH administration may improve bone formation and attenuate diabetes-aggravated bone loss by decreasing sclerostin expression in osteocytes of type 1 diabetic rats with periodontitis." (PMID 29544500, 2018). "Hazard ratios with 95% confidence intervals of type 2 diabetes mellitus (DM) incidence by plasma 25(OH)D levels after stratification for PTH levels, regular strenuous exercise, metabolic syndrome, and DM risk scores." (PMID 29672520, 2018). "Therefore, lower levels of PTH may induce a lower turnover state, and this status may be correlated with the higher risk of fracture in patients with diabetes." (PMID 26273297, 2015). "Furthermore, lower PTH concentration resulted in low bone formation, which may increase the risk of vertebral fractures in diabetes patients of both sexes." (PMID 26273297, 2015). "Additional factors linked to significant CAD included age, smoking status, diabetes, hypertension, eGFR, urinary albumin, phosphate, LDL-cholesterol, hsCRP, and intact PTH." (PMID 41597410, 2026). "Univariate analysis revealed notable associations between TyG index and factors such as age, gender, BMI, phosphorus, Cr, PTH, hypertension, diabetes, smoking status and drinking status." (PMID 41019331, 2025). "The highest prevalence of diabetes was observed in the high-turnover group, comprising nine (52.9%) patients with intact parathyroid hormone (iPTH) levels > 9 times the upper limit of normal." (PMID 40551948, 2025). "This study emphasized the significance of intact PTH in CKD5 patients and expanded earlier findings by demonstrating the similar link between intact PTH and diabetes in PD patients in southern China." (PMID 39791168, 2025). "This multicentre observational retrospective study emphasized the importance of Mg and diabetes on PTH in CKD5 patients in southern China." (PMID 39791168, 2025). "Model 3, which adjusted for additional comorbidities including hypertension and diabetes, confirmed the significance of baseline PTH levels ≥166 ng/L (HR 2.07, 95% CI 1.16–3.68, p = 0.01) as a predictive factor." (PMID 40429305, 2025). "Model 3 includes Model 2 + overweight/obese, hypertension, dyslipidemia, diabetes, serum 1,25(OH)2D, serum intact-parathyroid hormone, serum phosphate, serum phosphate, and daily physical activity." (PMID 41038963, 2025). "A study from the Atherosclerosis Risk in Communities (ARIC) cohort found that higher PTH levels were linked to more severe WMH, but this association disappeared after adjustment for traditional risk factors such as hypertension and diabetes." (PMID 41050279, 2025). "Key factors affecting pain included body mass index (BMI), hypertension (HT), diabetes mellitus (DM), and PTH levels." (PMID 41155999, 2025). "The final model, accounting for age, gender, BMI, phosphorus, Cr, PTH, hypertension, diabetes, smoking status and drinking status, revealed an effect magnitude of 0.907 (95% CI: 0.675 - 1.139, P-value < 0.001)." (PMID 41019331, 2025). "Threshold assessment was further conducted after adjusting for age, gender, BMI, phosphorus, Cr, PTH, hypertension, diabetes, smoking status and drinking status." (PMID 41019331, 2025). "Patients with diabetes with poor glycemic control (HbA1c > 6.5%) had higher VD (10.09 ± 4.93 vs. 9.82 ± 5.57 ng/mL) and PTH (58.9 ± 49.99 vs. 50.73 ± 34.01 ng/mL) levels compared to those with adequate control (p values not significant)." (PMID 40313432, 2025).
diabetes (continued). "The usual care group had slightly more male participants, slightly fewer white participants, slightly more participants with diabetes mellitus and higher parathyroid hormone concentration, but otherwise were well‐matched to the exercise intervention group." (PMID 40026059, 2025). "The strength and reliability of Model 3 were validated by additional subgroup analyses, which categorized OPF patients according to age, BMI, triglycerides, ALT, UA, diabetes, hypertension, monocyte, hemoglobin, platelet, and PTH levels." (PMID 39144661, 2024). "The final model adjusted for age, BMI, triglycerides, ALT, UA, diabetes, hypertension, monocyte, hemoglobin, platelet, and PTH level counts indicated an impact size of 0.07 (95% CI = 0.02 to 0.12, p = 0.0027) and −0.19 (95% CI = −0.29 to −0.09, p = 0.0003)." (PMID 39144661, 2024). "The threshold effect analysis further involved age adjustments, BMI, triglycerides, ALT, UA, diabetes, hypertension, monocyte, hemoglobin, platelet, and PTH." (PMID 39144661, 2024). "In a cross-sectional study of 80 patients on peritoneal dialysis in Canada, hypomagnesemia was associated with greater abdominal aortic calcification, independently of age, serum phosphate, parathyroid hormone, cholesterol, smoking history, and diabetes." (PMID 38256228, 2024). "The univariate analysis indicated a significant correlation between lumbar BMD, β-CTX, and other factors including age, BMI, triglycerides, ALT, UA, diabetes, hypertension, monocyte, hemoglobin, platelet, and PTH, particularly with APOA1." (PMID 39144661, 2024). "Upon comparing the data, we found similarities regarding age, initial creatinine levels, initial PTH levels, number of male patients, patients with diabetes, transplanted patients who had a second episode of infection." (PMID 35510838, 2023). "In patients with diabetes, PTH level, ferritin ≥ 800 and serum albumin were significantly associated with higher mortality." (PMID 36719878, 2023). "Significant associations were found: Vitamin D (25(OH)D) with trabecular parameters with possible synergy with A1C, parathyroid hormone with cortical parameters, BMI with cortical bone and failure load, and diabetes duration with trabecular area." (PMID 36936151, 2023). "Overall, these findings at the tissue level support the notion that established diabetes is a low bone remodeling disease; and that PTH/ABL reverse it towards a high bone remodeling condition with bone gain." (PMID 37076478, 2023). "This shows that vitamin D, BGP, T-PINP and BMD decrease with the increase of urine protein in patients with diabetes, while PTH and β-CTX increase with the increase of urine protein." (PMID 37250586, 2023). "Future studies will be required to establish the role of these conversely regulated genes in diabetes-induced bone disease and/or PTH/ABL action in bone." (PMID 37076478, 2023). "The interaction of diabetes with calcium intake on the suppression of PTH remained significant (p = 0.017, β = 0.53)." (PMID 38025039, 2023). "Both age and the proportion of patients with diabetes were significantly higher in the low PTH group than the values in the SHPT group." (PMID 35634511, 2022). "There were more patients with diabetes mellitus, old age, high systolic blood pressure, high serum intact parathyroid hormone (iPTH), elevated C-reactive protein, and high OPN levels in the AS group compared with the control group in hypertensive participants." (PMID 35010737, 2022). "History of fracture was positively correlated with age (r = 0.231, P = 0.000), PTH (r = 0.039, P = 0.014), diabetes (r = 0.044, P = 0.024), Cardio-cerebrovascular diseases (r = 0.105, P = 0.000) and chronic liver and kidney diseases (r = 0.043, P = 0.027)." (PMID 36404305, 2022). "According to Impact Analysis, proteinuria (normalized likelihood, NL=1.52), diabetes (NL=1.43), COPD (NL=1.35), male sex (NL=1.24), eGFR (NL=1.06), hypertension (NL=1.05), PTH (NL=1.02) increased CVD risk." (PMID 37675027, 2022).
diabetes (continued). "In this cohort study, we matched for age, sex, diabetes history, and duration of dialysis at baseline between the low PTH and SHPT groups to eliminate the cofounding effects of these known variables." (PMID 35634511, 2022). "In the present study, we investigated for the first time the three SNP polymorphisms of the LGALS3 gene and its correlation with hemoglobin levels, rate of glomerular filtration, level of parathyroid hormone, diabetes mellitus, and arterial hypertension." (PMID 35807161, 2022). "In the multivariate regression analysis, serum Ln(TMAO), HD vintage, with diabetic mellitus, age and plasma intact parathyroid hormone (iPTH) were independent determinant factors for VC in HD patients." (PMID 36384389, 2022). "Participants with higher VDMR were more likely to be White, less likely to be Black, less likely to have hypertension or diabetes, had lower concentrations of PTH, and had higher concentrations of 24,25(OH)2D3, 25(OH)D3, and total 25(OH)D." (PMID 36530185, 2022). "In Diabetes Mellitus secretion of Parathyroid Hormone (PTH) declines, resulting in decrease disrupted calcium homeostasis that is cellular calcium depletion occurs." (PMID 35611244, 2022). "The CAA haplotype was significantly more common in patients with diabetes, low hemoglobin level, and normal PTH level." (PMID 35807161, 2022). "Catheter exposure for > 90 days, diabetes, lower PTH, and lower BMI were uniquely among the top 15 predictors of longer-term death in the LatAm cohort, as well as other factors." (PMID 36273142, 2022). "For instance, our Medicare data set had no information on relevant clinical variables including duration of diabetes, hemoglobin A1c values, vitamin D and parathyroid hormone levels, and body mass index." (PMID 34705014, 2021). "The reported normal range of PTH based on healthy Chinese adults is 10.78–101.19 pg/mL after excluding parathyroid diseases, kidney diseases, diabetes, and other related diseases." (PMID 34948669, 2021). "The circulating calcium and phosphorus concentrations were comparable; however, the level of intact PTH and the incidence of diabetes were significantly increased in the high AS group." (PMID 33923139, 2021). "Gender, race, diabetes,CAD, RD, serum P, PTH, and albumin were associated with cardiovascular mortality byunivariate analysis." (PMID 33576763, 2021). "Summary of variants associated at genome-wide significance (P<5.0x10-8) with vitamin D concentrations, parathyroid hormone concentrations, and bone mineral density in the African American-Diabetes Heart Study cohort." (PMID 34014961, 2021). "As previous studies, we observed that patients with low PTH levels (< 150 pg/mL) had worse nutritional status including advanced age, diabetes mellitus, low serum creatinine, and phosphorus levels." (PMID 33514340, 2021). "Information on age, sex, plasma 25 (OH)D, serum calcium, serum phosphate, parathyroid hormone, dialysis period, hypertension, diabetes, ALT, AST, albumin, alkaline phosphates, and BMI was obtained from the medical records." (PMID 33791129, 2021). "A retrospective large study showed that the preoperative PTH level, the percentage of PTH reduction after the operation, and diabetes are influencing factors for the recovery of parathyroid function one week after discharge." (PMID 33882915, 2021). "Compared to women with high OC and high PTH, women with low OC and low PTH had the highest odds for diabetes and low HDL-C, and the lowest odds for hypercholesterolemia and high LDL-C." (PMID 33833796, 2021). "General (age, gender, BMI and PTH) and diabetes - specific parameters (disease duration, HbA1c) were introduced as independent variables in multiple regression analysis with lumbar and femoral neck BMD as outcome variables, respectively." (PMID 34362364, 2021).
diabetes (continued). "Weighted distributions of 25(OH)D and PTH differed significantly between white and black women when stratified by diabetes status and diabetes-related cardiometabolic comorbidities (all P values < 0.0001)." (PMID 34531372, 2021). "Circulating PTH levels can be affected by systemic metabolic disorders such as arterial hypertension and insulin resistance/diabetes." (PMID 32751307, 2020). "We observed a significant decrease in PTH levels from Day 1 to Day 3, as well as phosphorus levels from Day 3 to Day 7, in the patients with diabetes after they took the drug." (PMID 33352890, 2020). "Numbers of patients with chronic liver disease, CVA, diabetes mellitus, as well as serum levels of albumin, K, Ca, and parathyroid hormone, transferrin saturation, hemoglobin and platelets were similar between the groups." (PMID 31999778, 2020). "High BMD, old age, male sex, increased weight and height, diabetes, and high osteocalcin and uric acid levels were observed in patients with high serum sclerostin levels and an inverse relation was noticed between PTH and sclerostin." (PMID 31315601, 2019). "Sclerostin levels were associated positively with age, male sex, weight, height, diabetes, BMD, and serum uric acid levels and negatively with total Kt/V for urea, osteocalcin levels, and intact PTH levels." (PMID 31315601, 2019). "Age, weight, diabetes, osteocalcin levels, and intact PTH levels had marginally statistical significance (P > 0.05) or marginal effects (OR = ~ 1) on sclerostin levels." (PMID 31315601, 2019). "Univariate survival analysis revealed that factors that associated with NOAVN at transplantation were a BMI ≥ 26 kg/m2 (p = 0.0004), pre-transplant diabetes (p = 0.040), and PTH > 300 pg/mL (p = 0.044)." (PMID 30794689, 2019). "This study is the first to show that resistin and FGF23 are significantly associated, even on multiple regression analysis including renal function, PTH, vitamin D status, and markers of diabetes." (PMID 30228288, 2018). "Rats were divided into control (C), periodontitis (P), periodontitis treated with PTH (P + PTH), diabetes with periodontitis (DP), and diabetes with periodontitis treated with PTH (DP + PTH) groups." (PMID 29544500, 2018). "We did not observe significant between group differences with respect to diabetes, PTH, history of corticoid use, use of active Vitamin D medication, or Cinacalcet." (PMID 28199411, 2017). "On the contrary, PTH level increased significantly in diabetes duration >10 years group than that in control group and diabetes duration ≤10 years group." (PMID 29190676, 2017). "The 25OHD levels and BMDs at the femoral neck and total hip were significantly lower in diabetes than those in control subjects (P<0.01 and P<0.05); however, the PTH levels increased in the diabetes compared to control subjects." (PMID 29190676, 2017). "Patients with higher AAC grade were older, had more frequently diabetes mellitus and cardiovascular disease, had lower diastolic blood pressure, and had higher corrected calcium and lower intact parathyroid hormone levels." (PMID 28642879, 2017). "The study suggested possible beneficial actions of PTH at early stages of macrovascular disease in responses to diabetes and dyslipidemia." (PMID 28367447, 2017). "Demographic and anthropometric data, smoking, diabetes and metabolic syndrome (MetS), calcium (Ca), vitamin D, parathyroid hormone (PTH), uric acid and urine pH were compared in both groups." (PMID 28491855, 2017). "The results revealed that BMD at the femoral neck was negatively correlated with diabetes duration, HbA1c and PTH, whereas it was positively correlated with 25OHD." (PMID 29190676, 2017). "They reported a significant positive correlation between PTH and OC and a positive correlation between OC and urine albumin excretion in diabetes patients." (PMID 27826545, 2016).
diabetes (continued). "The TG/HDL-C ratio was an independent determinant of FMD (β = 0.25 p = 0.02) together with the TG, HDL-C, hsCRP, serum albumin, phosphate levels, SBP, PTH, eGFR and the presence of diabetes mellitus." (PMID 25885289, 2015). "Women with diabetes had a mean PTH of 46.0 ± 16 ng/l and the corresponding level in men was 47.4 ± 18 ng/l (p = 0.30 for comparison between genders)." (PMID 26078787, 2015). "In the multivariate analysis including sex, body mass index (BMI), age, PTH, eGFR, FePi, serum phosphate, serum calcium, total cholesterol, systolic blood pressure, proteinuria, diabetes and smoking, only eGFR and smoking were independent predictors of FGF23." (PMID 25700931, 2015). "Associations have been inconsistent for coronary calcification score and serum intact PTH, C-reactive protein, serum calcium, serum creatinine, cholesterol, diabetes, smoking, and hypertension." (PMID 26269747, 2015). "The relationships of PTH levels with the serum Ca/Mg ratio and serum Ca × P were analyzed via multivariate analysis using the General Linear Model, with sex, age, diabetes, and eGFR as the adjusted variables." (PMID 26273297, 2015). "The TG/HDL-C ratio was an independent determinant of FMD (β = −0.25 p = 0.02) along with TG, HDL-C, hsCRP, serum albumin, phosphate levels, systolic blood pressure, PTH, eGFR and the presence of diabetes mellitus." (PMID 25885289, 2015). "In particular, similar to a variety of other disorders, such as diabetes and hypertension, the success of anti-osteoporotic therapy is essentially dependent on a specific target PTH level (<60 pg/mL in uor case)." (PMID 23227959, 2012). "We also performed a stepwise linear regression model on the FGF23 adjusted for age, gender, race, smoking, hypertension, diabetes, body mass index, 25(OH)D, total calcium, phosphorus, log PTH, urea, and creatinine clearance." (PMID 22590632, 2012). "Advanced age, diabetes mellitus, smoking, low parathyroid hormone level, elevated serum ferritin, elevated serum glucose, and low serum creatinine levels increased the risk for PAD." (PMID 22943313, 2012). "In patients with CKD FGF23 is significantly associated with proteinuria and smoking, along with other, already established associations, like eGFR (inverse relation), plasma phosphate level, PTH, history of cardiovascular disease and diabetes mellitus." (PMID 22530966, 2012). "The information collected for each patient included age, body mass index, creatinine, history of diabetes and hypertension, and levels of vitamin D and PTH." (PMID 22363866, 2011). "The chi-square test, Pearson correlation analysis, hierarchical regression analysis, and t-test were used to explore the relationships between Ln_PTH and gender, diabetes history, Mg, P, Ca, albumin (Alb), red blood cells (RBC), hemoglobin (Hb), white blood cells (WBC), and platelet (Plt)." (PMID 39791168, 2025). "In a Cox regression analysis, time to fragility fracture was independently associated with serum Mg <2.2 mg/dL (P < .001), in a model adjusted to age, female gender, HD vintage, diabetes mellitus, body mass index, albumin, parathyroid hormone, active vitamin D therapy and the presence of VC." (PMID 40008355, 2025). "Even though this was observational research, this conclusion is significant because we emphasized the effect of Mg and diabetes on PTH in patients with CKD5 and suggested that Mg supplement may aid in improving intact PTH level regulation in CKD patients." (PMID 39791168, 2025). "Younger age, absence of diabetes, high baseline alkaline phosphatase and PTH were independent risk factors for PTH > 600 pg/mL after 1 year of HD." (PMID 40525801, 2025). "In the survival submodel, which accounted for time-varying PTH, along with calcium, phosphorus, age ≥65 years, sex, diabetes, hypertension, and medication use, time-varying PTH was significantly associated with an increased risk of IHD (coefficient = 0.001, 95% CI 0.0001–0.002, p = 0.022)." (PMID 40429305, 2025).